RNU6-828P (RNA, U6 small nuclear 828, pseudogene)
Gene: Small nuclear RNA gene on chromosome 1 (10,163,268 to 10,163,374, forward strand). Ensembl gene ENSG00000201746.
Homologues: Orthologues: chimpanzee U6 (100% identical), macaque U6 (90% identical), dog U6 (82% identical), guinea pig U6 (80% identical), rat LOC120099419 (72% identical), mouse Gm55244 (68% identical). Paralogues in human: RNU6-38P (88% identical), RNU6-29P (87% identical), RNU6-1145P (86% identical), RNU6-28P (86% identical), RNU6-47P (86% identical), RNU6-74P (86% identical), RNU6-1011P (85% identical), RNU6-242P (85% identical), RNU6-25P (85% identical), RNU6-33P (85% identical), RNU6-41P (85% identical), RNU6-618P (85% identical), and 1286 more.